BRAF (B-Raf proto-oncogene, serine/threonine kinase)
Diseases named in the same sentence as BRAF in open-access papers (continued):
Sharing a sentence is not in itself a finding about the gene and the disease.
lymph node metastasis (continued). "In addition, the frequency of the BRAF V600E mutation was significantly different in the central and lateral neck lymph nodes of patients with lymph node metastasis, which is consistent with previous studies." (PMID 24396464, 2014). "In addition, the frequency of the BRAF V600E mutation was significantly different in the central (75.3%) and lateral neck (49.3%) lymph nodes of patients with lymph node metastasis." (PMID 24396464, 2014). "Moreover, the BRAF V600E mutation is significantly different in central lymph nodes and lateral neck lymph nodes of patients with lymph node metastasis." (PMID 24396464, 2014). "In addition, the BRAF V600E mutation was significantly different in the central lymph nodes and lateral neck lymph nodes (75.3 vs. 49.3%; P=0.002) of patients with lymph node metastasis." (PMID 24396464, 2014). "Thus, BRAF mutations were found in 15/42 (35.7 %) of subcutaneous metastases, 12/20 (60.0 %) of lymph node metastases, but only in 3/22 (13.6 %) of the visceral metastases examined (p = 0.007)." (PMID 23673558, 2013). "Therefore, the relationship between BRAF V600E mutation and lymph node metastasis was inconsistent in different cohorts, which may be due to the different genetic backgrounds of different races." (PMID 38734621, 2024). "However, it has always been controversial whether there is a correlation between BRAF V600E mutation and neck lymph node metastasis." (PMID 34307677, 2021). "Tumors harboring BRAF+TERT co-mutations demonstrated particularly aggressive features, with 60% lymph node metastasis (6/10 cases) and a mean tumor diameter of 16.8 mm." (PMID 40805132, 2025). "This identifies Gender, Psammoma Bodies, Non-BRAF mutation, Tumor Size, and SIRI as independent predictors of lymph node metastasis." (PMID 40964092, 2025). "Lymph node metastases were found in 7 (20.6%) patients receiving PD‐1 and 3 (9.4%) patients receiving BRAF + MEK treatment." (PMID 40331873, 2025). "Its potential in predicting lymph node metastasis, as well as gene mutations such as KRAS, NRAS, and BRAF has been evaluated." (PMID 41295561, 2025). "BRAF V600E is associated with adverse features, including tall cell histological subtypes, macroscopic extrathyroidal extension (ETE), lymph node metastasis, advanced tumor stages, and higher recurrence rates." (PMID 40805249, 2025). "One retrospective study found that lymph node metastasis (LNM) and BRAF significantly heightened the mortality risk in TC." (PMID 40149275, 2025). "The combination of BRAF and RAS mutations led to 100% malignancy (3 PTCs and 1 FTC), half of which had lymph node metastasis." (PMID 38277563, 2024). "Among the cases with BRAF mutations, 99.2% were defined as malignant PTC with 68.3% developed lymph node metastasis." (PMID 38277563, 2024). "A plethora of literature suggests BRAF mutation in DTC increases the risk of multifocality, extrathyroidal extension, and lymph node metastasis." (PMID 37190300, 2023). "Mutations in BRAF and the TERT promoter were significantly associated with lower iodine avidity for lymph node metastases (18-fold and 10-fold, respectively)." (PMID 37352166, 2023). "The presence of both the BRAF V600E and TERT mutations is synergistic and substantially increases the risk of lymph node metastasis, recurrence, and disease-specific mortality rates." (PMID 37623013, 2023). "BRAF mutation-positive PTC have been reported to have a higher frequency of extra-thyroidal extension, lymph node metastasis and tumor recurrence, which has been correlated with tumor death." (PMID 37544981, 2023). "Mutation in the BRAF oncogene BRAFV600E is widely associated with advanced cancer, lymph node metastasis (LNM), and decreased patient 10-year survival rate." (PMID 36009596, 2022). "Multivariate logistic analysis of lymph node metastasis and clinicopathological features showed that KDM1A expression, age and BRAF mutation were independent prognostic factors for lymph node metastasis in PTC." (PMID 35198054, 2022).
lymph node metastasis (continued). "Mutation of the BRAF oncogene has been associated with extrathyroidal invasion (ETE), lymph node metastasis (LNM), and decreased 10-year survival." (PMID 36555268, 2022). "PTC harboring BRAF V600E mutation had the highest rates of lymph node metastases and extra-thyroid extension, while PTMC harboring WT-BRAF had the lowest rates." (PMID 35197932, 2022). "Diagnosis of all of the PTC patients [including lymph node metastasis (LNM), HT, and BRAF V600E mutation] was histologically confirmed by two independent pathologists." (PMID 34805166, 2021). "In the phase III COMBI-AD trial, 870 patients with stage IIIA (lymph-node metastasis > 1 mm), B and C (AJCC 7th edition) with proven BRAF mutation (either V600E or V600K) were randomized to receive either treatment with the two oral drugs or placebo." (PMID 34884176, 2021). "Previous studies have described an association of BRAF V600E mutation with aggressive features of PTC, including macroscopic extrathyroidal extension (ETE), lymph node metastasis (LNM), advanced stage, and disease recurrence." (PMID 34742355, 2021). "Risk ratios in BRAF (V600E)-positive patients were 1.93 for PTC recurrence, 1.32 for lymph node metastasis, 1.71 for ETE, 0.95 for distant metastasis, and 1.70 for advanced stage AJCC III/IV." (PMID 34475951, 2021). "Based on various reports, BRAF and TERT mutation are associated with the older age, female gender, bigger tumor size, extrathyroidal extension, lymph node metastasis, multifocality, advanced stage, and recurrence." (PMID 33247684, 2020). "These authors found that other factors, such as the presence of lymph node metastases, extrathyroidal invasion, or histologic type of PTC, provide higher accuracy in predicting disease outcome than BRAF mutation status alone." (PMID 32316638, 2020). "Based on the correlations between the driver gene (NF1, BRAF, and RAS) alterations and clinical characterizations (ulceration, lymph node metastasis), patients harboring more mutations were prone to poor prognosis." (PMID 32083130, 2020). "PTCs with cervical lymph node metastases were verified pathohistologically, and primary tumors and LNM were examined for the BRAF V600E mutation." (PMID 33064665, 2020). "and eIF5A2 overexpression was related to extrathyroidal extension, lymph node metastasis, TNM staging, T classification and BRAF V600E mutation." (PMID 33200656, 2020). "BRAF, RAS, and NF1 mutations were significantly associated with lymph node metastasis or presence of ulceration, implying that these cancer driver genes were independent prognostic factors." (PMID 32083130, 2020). "Regarding DFS, BRAF V600E positivity as well as age, sex, Breslow thickness, ulceration, and lymph node metastasis were included in the multivariate analysis." (PMID 32143442, 2020). "Coexistence of BRAF V600E and TERT promoter mutations were significantly correlated with lymph node metastasis, multifocality, distant metastasis, tumor recurrence, extrathyroidal extension, and dead of disease." (PMID 31300059, 2019). "Lymph node metastasis (pN1) was demonstrated in the minority of PTC + HT cases which all presented with a wild-type BRAF status." (PMID 30666518, 2019). "In contrast, Oler and Cerutti reported that the BRAF (V600E) mutation was associated with tumour size, ETE, lymph node metastasis, high risk of recurrence and mortality in PTC patients." (PMID 30916170, 2019). "BRAF V600E-positive patients had more lymph node metastases reoperations due to radiorefracterity than RET/PTC-positive patients, but the difference was not statistically significant." (PMID 31085772, 2019). "Statistically meaningful association is found between TERT promoter mutations and older age, larger tumor size, extrathyroidal extension, lymph node metastasis, distance metastasis, advanced TNM stage, recurrence, and BRAF V600E mutation." (PMID 30024548, 2018).
lymph node metastasis (continued). "Overall, the features included age, gender, tumor size, extrathyroidal extension, lymph node metastasis, multifocality, distance metastasis, TNM stage, recurrence, and the relationship with BRAF mutation." (PMID 30024548, 2018). "Despite good prognosis, certain features such as lymph node metastasis (LNM) and BRAF V600E mutation are associated with a poor outcome." (PMID 29713312, 2018). "Massive prognostic parameters for recurrence of PTMC have been identified in previous studies, such as male gender, age <45, ETE, multifocality, primary tumor size, BRAF, T3 tumor, and lymph node metastasis." (PMID 28741199, 2017). "The BRAF V600E mutation is associated with extra-thyroidal extension, advanced TNM stage, lymph node metastasis, multifocality, and recurrence in a meta-analysis study." (PMID 27447554, 2016). "The presence of HT in PTC has been associated with favorable prognostic features, such as lower rates of lymph node metastasis, extrathyroidal extension, and TNM stage, and lower frequency of BRAF V600E mutation." (PMID 25983754, 2015). "For example, lymph node metastasis and AJCC stage I disease had positive associations with BRAF mutation by BigDye Terminator sequencing (P = 0.012 and P = 0.016, resp)." (PMID 26448939, 2015). "Larger tumor size, extrathyroidal invasion, lymph node metastasis, and more advanced TNM stage were associated with the BRAF mutation." (PMID 24559116, 2014). "A number of studies have reported that BRAF mutation was associated with aggressive PTC characteristics, such as extrathyroidal extension, lymph node metastasis, tumor recurrence, decreased survival, and need for cervical reoperation." (PMID 23690767, 2013). "Statistical analysis showed that BRAF-positive patients tended to develop lymph node metastasis." (PMID 40469184, 2025). "Multiple lesions, capsular invasion, and lymph node metastases did not significantly correlate with the presence of a BRAF mutation in our study." (PMID 40028210, 2025). "However, they had a lower rate of extrathyroidal extension (ETE), lymph node metastasis (LNM), and BRAF mutation (P < 0.05)." (PMID 40269951, 2025). "The BRAF V600E mutation is also associated with sentinel lymph node metastasis but not with ulceration or the host immune response measured by TILs, as reported by some of the included studies." (PMID 40507250, 2025). "The BRAF V600E AF has recently been implicated in the metastatic potential of PTC, with studies suggesting that higher AF is associated with poorer clinical outcomes and advanced tumor staging due to increased invasiveness and lymph node metastases." (PMID 40805249, 2025). "The results showed that BRAF V600E mutation abundance was significantly higher in the CLNM group than in the non-metastatic group (median 23% vs. 17%, p < 0.001), suggesting a close association between higher mutation abundance and lymph node metastasis." (PMID 41228353, 2025). "These cases often exhibited adverse clinicopathological features such as capsular invasion, lymphatic invasion, angioinvasion, minimal ETE, infiltrative and invasive capsule status, high AJCC pT stage, BRAF V600E mutations, TERT promoter mutations, lymph node metastasis, and synchronous metastasis." (PMID 40312532, 2025). "The correlation between the methylation levels of SCNN1B and the clinicopathological parameters of the CRC patients, such as age, sex, tumour differentiation, tumour stage, lymph node metastasis, tumour localization, RAS mutation, BRAF mutation, and MSI status, was evaluated." (PMID 39415304, 2024). "In our patient, however, the lymph node metastasis was assigned to the BRAF positive PTC of 11 mm." (PMID 39449865, 2024). "In contrast, a high activity of RET (presence of CCDC6::RET rearrangement or high expression) and low activity of BRAF (absence of BRAFV600E or its low expression) were associated with lymph node metastasis." (PMID 37188126, 2023).
lymph node metastasis (continued). "The result of this meta-analysis also did not support the relationship between UIC and the BRAF mutation and lymph node metastasis (LNM) of PTC patients." (PMID 36387866, 2022). "The rates of lymph node metastasis were 21.4% (18/84), 24.8% (38/153), 38.9% (7/18), and 43.8% (14/32) for PTMC harboring wild type (WT)-BRAF, PTMC harboring BRAF V600E mutation, PTC harboring WT-BRAF, and PTC harboring BRAF V600E mutation, respectively." (PMID 35197932, 2022). "CNV, BRAF, and tumor size in predicting lymph node metastasis." (PMID 36313748, 2022). "After restricting the sample to those with BRAF-mutant versus RET/NTRK fusion status, statistically significant associations were still found among age, AJCC N (lymph node metastasis) and M (distant metastasis, all pulmonary) categories as well as remission at 1 year (P value < .05)." (PMID 35015563, 2022). "BRAF mutations were more prevalent in tumors larger than 1 cm, this association was also described by Li 2012 and Kim 2012.11, 26 Comparison of lymph node metastasis and BRAF mutation did not reveal any correlation (p = 0.423)." (PMID 32972866, 2022). "Our multicenter study supports an association of BRAF V600E with extrathyroidal extension (68.6% vs. 31.4%; p<0.001) and lymph node metastasis (64.8% vs. 35.2%; p=0.004), but not with distant metastasis (42.9% vs. 57.1%; p=0.163)." (PMID 36714606, 2022). "The groups were analysed for the presence of a BRAF V600E mutation and aggressive features, including macroscopic extrathyroidal extension (ETE), lymph node metastasis (LNM), and high-risk histological features (tall cell, columnar cell, hobnail, solid/trabecular, and diffuse sclerosing)." (PMID 34742355, 2021). "It revealed 3 significant prognosis-related variables: lymph node metastasis, BRAF mutations and NRG1 deletions, where the significance level for lymph node metastasis was much close to 0.05, and limited to the number of samples, we did not perform an in-depth analysis on it." (PMID 34044811, 2021). "Specifically, we considered lymph node metastases, age, number of total non-silent mutations, number of CpGT mutations, BRAF-RAF score, ERK score, miRNA cluster, RPPA cluster, ploidy, differentiation score, and follicular component." (PMID 33291668, 2020). "Compared to patients in the L-immunity group, patients in the H-immunity group had an advanced American Joint Committee on Cancer (AJCC) stage, advanced T classification, lymph node metastasis, higher tall-cell PTC and lower follicular PTC proportions, more BRAF mutations and fewer RAS mutations." (PMID 33193087, 2020). "The quantitative analysis of BRAF mutant alleles showed a significant difference between PTCs presenting with lymph node metastases as compared to PTCs without metastases (27.6% vs. 18.4% respectively; p = 0.03)." (PMID 31810221, 2019). "Of note, MSK-IMPACT testing was done retrospectively after the patient’s death, on both the supraclavicular lymph node metastasis, which had been found to harbor BRAF K601E, and on the left cervical lymph node excised immediately prior to start of treatment with trametinib." (PMID 31158244, 2019). "Lymph node metastasis was present in 4575 (43.4 %) of 10,542 patients with BRAF mutations and in 2405 (32.5 %) of 7394 patients without BRAF mutations." (PMID 27600854, 2016). "The risk of PTC recurrence is mainly related to the presence of lymph node metastases and extrathyroidal invasion, whereas no impact of BRAF V600E mutation has been demonstrated." (PMID 26177218, 2015). "The other patient had a discordant BRAF mutation status between two regional metastases, that is, a lymph node metastasis that did not display BRAFV600E and a skin metastasis with the mutation." (PMID 25526463, 2014).
lymph node metastasis (continued). "In BRAF-mutant patients, bilaterality was strongly associated with aggressive features such as larger tumor size, gross ETE, and lymph node metastasis and could serve as an independent risk factor for recurrence, corresponding to an HR of 2.23 (95% CI: 1.65,4.76; p = 0.020)." (PMID 42058723, 2026). "Our results suggest that beyond BRAF V600E AF, genetic variability, age and ethnicity may contribute to the heterogenous rate of carcinogenic cell proliferation, tumor growth, and subsequent lymph node metastasis." (PMID 40805249, 2025). "For example, BRAF V600E mutation is strongly associated with aggressiveness and poor prognosis of PTC, while the expression levels of certain miRNAs may be associated with the risk of lymph node metastasis and recurrence." (PMID 40123892, 2025). "Meta-analyses have shown that patients with a BRAF V600E mutation, especially in combination with a TERT promoter mutation, have a higher risk of unfavorable clinicopathological parameters such as extrathyroidal tumor spread, lymph node metastasis, and a higher TNM stage." (PMID 38616265, 2024). "The prevalence of BRAF V600E mutation was 38.4% and was not significantly linked to cases with high-risk biological features such as clinically apparent lymph node metastasis, massive extrathyroid extension, advanced age, distant metastases at surgery, and advanced stage." (PMID 34734568, 2021). "Lymph node metastases was equally distributed in patients with or without BRAF V600E mutation." (PMID 34734568, 2021). "In addition to the traditional clinicopathological risk factors, specific molecular profiles (e.g., BRAF, TERT, and RET) may be used to predict the risk of extrathyroidal extension and lymph node metastases." (PMID 33392186, 2020). "V600E BRAF mutation could be demonstrated in 7/34 (20.6%) PTCs with lymph node metastasis (pN1) while none of the metastatic PTC + HT cases presented with the mutant-type BRAF status (0/4, 0%)." (PMID 30666518, 2019). "A biopsy of the lymph node metastasis showed the absence of a BRAF mutation." (PMID 30133176, 2018). "However, the frequency of the BRAF V600E mutation was not correlated with gender, tumor size, lymph node metastasis or location of the lesion." (PMID 24396464, 2014). "However, the BRAF V600E mutation was not correlated with gender, tumor size, lymph node metastasis and location of the lesion." (PMID 24396464, 2014). "Patient 4 represents a lymph node metastasis positive for BRAFV600E, sampled after the development of drug resistance to BRAF/MEK inhibitors." (PMID 30290811, 2018). "Although not statistically significant, trends were observed for higher BRAF V600E AF in tumors with lymph node metastasis (mean AF: 25.4) compared to those without (mean AF: 16.67, p = 0.08)." (PMID 40805249, 2025). "In terms of lymph node metastases (LNM) before first adjuvant therapy, clinically detectable LNM outnumbered occult LNM with 18 patients (52.9%) under PD‐1 and 15 patients (46.9%) under BRAF + MEK therapy." (PMID 40331873, 2025). "In univariable analyses, lymph node metastasis (p = 0.964 in DTC, p = 0.410 in PTC) and BRAF V600E mutation (p = 0.331 in DTC, p = 0.253 in PTC) were not selected to multivariable analysis with p-values > 0.2." (PMID 37948420, 2023). "We calculated the adjusted hazard ratios (AHRs) (adjusted with age at diagnosis, sex, tumor size, extrathyroidal invasion, lymph node metastasis) for risk of recurrence in each category of DRS with and without BRAF mutation." (PMID 36714606, 2022). "CtDNA analysis of patient ID12 with a BRAF mutation showed a high MAF level (≥1%) at baseline with no longer detectable MAF and radiologically completely regressed lung and lymph node metastases, but new bone lesions developed during targeted therapy." (PMID 34205831, 2021). "Second, the perioperative MAF of BRAF V600E was not correlated with tumor markers or lymph node metastasis but was correlated with tumor diameter." (PMID 34168268, 2021).